ZNF324 (zinc finger protein 324)
Description:
May be involved in transcriptional regulation. May be involved in regulation of cell proliferation.
Synonyms: ZNF324A; ZF5128
Tractability: PROTAC: ubiquitination databases record sites on it.
Gene: Protein-coding gene on chromosome 19 (58,467,056 to 58,475,436, forward strand). Ensembl gene ENSG00000083812.
Subcellular location: Nucleus
Subcellular location (Human Protein Atlas): Cytosol; Nuclear membrane; Nucleoplasm
Pathways (Reactome):
Gene expression (Transcription): Generic Transcription Pathway; Regulation of endogenous retroelements by KRAB-ZFP proteins
Gene Ontology:
Molecular function: DNA-binding transcription factor activity, RNA polymerase II-specific; RNA polymerase II cis-regulatory region sequence-specific DNA binding
Biological process: cell population proliferation; G1/S transition of mitotic cell cycle; regulation of transcription by RNA polymerase II; regulation of DNA-templated transcription
Cellular component: nucleus
Genetic constraint (gnomAD): Loss-of-function variants: 3 observed, 9.13 expected, observed/expected ratio (o/e) 0.33, 90% interval 0.15 to 0.85. That is too few expected variants to judge how well the gene tolerates losing a copy. Missense variants: 763 observed, 766.16 expected, observed/expected ratio (o/e) 1, 90% interval 0.94 to 1.06. Synonymous variants: 430 observed, 332.97 expected, observed/expected ratio (o/e) 1.29, 90% interval 1.19 to 1.4.
Homologues: Orthologues: chimpanzee ZNF324 (99% identical), macaque ZNF324 (90% identical), mouse Zfp324 (71% identical), rat Zfp324 (70% identical), Drosophila melanogaster dwg (21% identical), Drosophila melanogaster CG6654 (21% identical), tropical clawed frog znf770 (16% identical), zebrafish 42sp43 (15% identical), Caenorhabditis elegans pat-9 (10% identical). Paralogues in human: ZNF324B (85% identical), ZBTB47 (25% identical), ZNF513 (24% identical), ZNF652 (21% identical), GTF3A (19% identical), ZUP1 (10% identical).